INS (insulin)
Diseases named in the same sentence as INS in open-access papers (continued):
Sharing a sentence is not in itself a finding about the gene and the disease.
type 2 diabetes (continued). "The enzyme dipeptidyl peptidase 4 (DPP4) can rapidly degrade glucagon-like peptide 1 (GLP-1), which increases insulin secretion and improves insulin sensitivity, making it a promising therapeutic target for type 2 diabetes." (PMID 36477638, 2022). "Lastly, the efficacy and safety of insulin degludec/liraglutide (IDegLira) was evaluated when added-on to SGLT2i therapy in patients with inadequately controlled type 2 diabetes." (PMID 35217772, 2022). "DM comprises numerous types, including insulin-deficient type 2 diabetes mellitus (T2DM), which will account for around 90% of cases and may affect approximately 300 million people around the globe by 2025." (PMID 36014440, 2022). "People with type 2 diabetes, an intellectual disability and using insulin, should be offered a flash glucose monitor (NICE NG28, 2022)." (PMID 35983585, 2022). "Type 2 diabetes, for example, involves both the alteration of insulin effects in peripheral tissues and the impairment of glucose-stimulated insulin secretion (GSIS)." (PMID 36012639, 2022). "Variants in IGF2BP2 have been previously found to be significantly associated with alterations in insulin secretion and resistance, and IGF2BP2 was found upregulated in the β-cells of patients with type 2 diabetes." (PMID 35761192, 2022). "On current trends, the boom in insulin treatment of type 2 diabetes is ending, and other therapies are becoming more profitable." (PMID 35275238, 2022). "Strength training therefore is recommended in type 2 diabetes patients as it improves insulin sensitivity and forms a logical starting point to increase muscular strength for future aerobic challenges." (PMID 36225127, 2022). "Previous work has also shown that clinical inertia leads to the delay of treatment intensification in people with type 2 diabetes and contributes to delays in starting treatment with insulin." (PMID 35120182, 2022). "The scope of the current study was to investigate both biomarkers’ trajectories in patients with type 2 diabetes treated with insulin combined either with metformin or placebo." (PMID 35379238, 2022). "This occurs when the body cannot produce enough insulin during pregnancy, and these women are more likely to later develop type 2 diabetes due to insulin resistance." (PMID 35300109, 2022). "All these results are of great significance for researching glucose metabolism and insulin response in skeletal muscle, which will provide new sight to treat type-2 diabetes." (PMID 35806430, 2022). "Metformin is the most used drug for type II diabetes that lowers glucose by stimulating insulin sensitivity and inhibiting gluconeogenesis." (PMID 36293505, 2022). "As we pointed out previously, MCH, in addition to increased feeding, regulates glucose homeostasis and insulin sensitivity, suggesting its potential as a target for the combined treatment for both obesity and type 2 diabetes." (PMID 35269579, 2022). "A 2019 meta-analysis reported that short-term vitamin D interventions in patients with type 2 diabetes improve HbA1c levels, and insulin sensitivity, thereby improving glycemic control." (PMID 35844355, 2022). "Blood levels were lower in parameters for NAFLD (e.g., alanine aminotransferase, and triglyceride), type 2 diabetes (e.g., glucose and insulin), and renal dysfunction (e.g., blood urea nitrogen and creatinine) by the KO treatments." (PMID 36005486, 2022). "InsR sensitizers increase insulin sensitivity for patients with type 2 diabetes and lower glucose levels for patients with type 1 disease." (PMID 35502441, 2022). "PPARγ agonists such as thiazolidinediones (TZDs) have been used in type 2 diabetes treatment to increase insulin sensitivity." (PMID 36339572, 2022). "It is currently accepted that type 2 diabetes originates from concomitant-compromised metabolism which induces inflammation and impaired insulin responsiveness, leading to deviated signaling homeostasis." (PMID 35954764, 2022).
type 2 diabetes (continued). "Coincidentally, FoxO6 has been shown to be involved in the dietary obesity and type 2 diabetes of animals via insulin resistance." (PMID 35883386, 2022). "The idea of influencing emotional behaviors with insulin dates back a century, when psychiatrists used insulin to cure mental illnesses by inducing a coma or as a shock treatment." (PMID 36232867, 2022). "In the INSPIRE pilot study we found that DMR combined with GLP-1RA successfully replaced insulin therapy in 69% (11/16) of patients with type 2 diabetes at 6 months and in 53% of patients at 18 months." (PMID 36138441, 2022). "In particular, insulin is prescribed with greater frequency in type 1 diabetic patients, although it is also used in some cases of type 2 diabetes, namely those inefficiently controlled by other drugs." (PMID 36359343, 2022). "Lixisenatide is a 44 amino acids glucagon-like peptide-1 agonist marketed by Sanofi and used in the treatment of type 2 diabetes to increase insulin secretion." (PMID 35688894, 2022). "This is in line with a clinical trial conducted in Australia, suggesting that fish oil enriched with DHA reduces insulin resistance and thereby helps to prevent type 2 diabetes." (PMID 36414942, 2022). "A key example is the role muscle plays in insulin sensitivity and the age-related disease, type 2 diabetes (T2D)." (PMID 36435511, 2022). "In this prospective, open-label, randomized, parallel-group study, 63 patients with type 2 diabetes received metformin and insulin glargine U100 for 12 weeks." (PMID 35171918, 2022). "Central obesity, notably excessive visceral fat, is associated with multiple metabolic alterations affecting blood cholesterol, glucose, and insulin levels, that can lead to cardio- and cerebrovascular disease and Type 2 diabetes." (PMID 35303671, 2022). "It is widely recognized that a close relationship exists between PGC-1α activity, insulin sensitivity, and the prevention of type 2 diabetes, most likely due to the essential role of PGC-1α in mitochondrial biogenesis and glucose/fatty acid metabolism." (PMID 35740043, 2022). "This is the first randomized, placebo‐controlled trial addressing the impact of long‐term, bedtime melatonin treatment on insulin sensitivity and β‐cell function in male patients with type 2 diabetes." (PMID 35619221, 2022). "We also observed 1 new diagnosis of hypertension, while 1 patient with pre‐existing type 2 diabetes and hypertension required escalation of antihypertensive therapy and the initiation of insulin." (PMID 35658515, 2022). "Thirty-one patients presented type 2 diabetes with oral medication and one patient presented type 1 diabetes with insulin treatment." (PMID 36143129, 2022). "In Asian Indians with young-onset diabetes, after adjustment for family history of type 2 diabetes, sex, insulin sensitivity and HDL-cholesterol, stimulated C-peptide was 492 pmol/ml (IQR 353–616, p<0.0001) lower in lean compared with obese individuals." (PMID 35247066, 2022). "Fasting insulin was again identified as an exception with effects that indicated partial mediation by liability to type 2 diabetes and an estimated proportion mediated of 70%." (PMID 35129650, 2022). "Previous studies suggest the involvement of TMEM163 in insulin secretion and type 2 diabetes pathogenesis." (PMID 35207731, 2022). "Although additional studies are needed for confirmation, our study underscores the potential role of adipose-derived EV-miRNAs in the regulation of fat redistribution and insulin function in people with type 2 diabetes undergoing pioglitazone treatment." (PMID 36120427, 2022). "Autophagy is a relevant regulatory signaling pathway for type 2 diabetes and is closely related to glucose and lipid metabolism, in addition to secretion of insulin." (PMID 36529747, 2022). "A similar study in eastern Ethiopia showed that metformin and insulin account for 37.2% and 16.2% of frequently used medications for type 2 diabetes, respectively." (PMID 35742447, 2022).
type 2 diabetes (continued). "Studies reported good treatment efficacy as well as increased peripheral insulin sensitivity in patients with type 2 diabetes." (PMID 35296331, 2022). "A total of eighteen had T1D, 5 had insulin-treated T2D, and one patient had maturity onset diabetes of the young (MODY)." (PMID 35433783, 2022). "Type 2 Diabetes (T2D) is a heterogeneous disease which most commonly presents as impaired insulin secretion or low insulin sensitivity." (PMID 36246869, 2022). "This disease can be classified into two categories: type 1 diabetes, in which insulin is no longer produced by pancreatic β cells because of their malfunction, and type 2 diabetes, characterized by the increase of insulin resistance, leading to hyperglycemia." (PMID 35160077, 2022). "The metformin in type 2 diabetes (Mity) trial is the largest trial of metformin vs placebo in addition to standard regimen of insulin in 502 women with type 2 diabetes during pregnancy." (PMID 35380983, 2022). "It protects mitochondria from oxidative stress induced by lipids and modulates insulin sensitivity, making it a potential player in type 2 diabetes development." (PMID 35323702, 2022). "Remote glucose monitoring has been utilized previously for adults with type 2 diabetes, and for children with T1D utilizing insulin pumps or CGM devices." (PMID 35037887, 2022). "Type II diabetes (T2D) is a metabolic disorder characterized as reduced secretion of insulin or insulin resistance resulting in persistent hyperglycemia (Asmat, Abad, 2016)." (PMID 35444531, 2022). "For both groups, mean fasting insulin values were in the range of mild to moderate hyperinsulinemia, and mean fasting glucose values were below the threshold for type 2 diabetes." (PMID 35458181, 2022). "Certainly, insulin is prescribed for patients with type 2 diabetes (T2D) with poor glycemic control, having a long duration with T2D and being prone to microvascular and macrovascular complications." (PMID 35637232, 2022). "Metformin is a first-line oral hypoglycemic agent for treating Type-2 diabetes, which inhibit gluconeogenesis in livers via strengthening hepatic sensitivity to insulin so as to bring down the levels of insulin and glucose in blood circulation." (PMID 35799755, 2022). "In general, oxidants have various inputs into regulating insulin signaling to the extent that type 2 diabetes is being considered as a “redox disease”." (PMID 35453469, 2022). "Beta-cell-specific influential genes are enriched in GO terms including glucose homeostasis and regulation of insulin secretion, as well as KEGG pathways including insulin secretion, maturity onset diabetes, etc.." (PMID 35709291, 2022). "Post-training insulin-stimulated GDR was ~30% lower in men with type 2 diabetes compared to both obese and lean men (p<0.01)." (PMID 36387850, 2022). "We investigated the metabolic effects of long‐term melatonin treatment in patients with type 2 diabetes including determinations of insulin sensitivity and glucose‐stimulated insulin secretion." (PMID 35619221, 2022). "Because skeletal muscle is the major site of insulin-mediated glucose uptake in the postprandial phase, the defect of skeletal muscle IR was suggested be the pathogenesis of the development of type 2 diabetes." (PMID 34983489, 2022). "When pancreatic beta cells fail to maintain the enhanced level of insulin secretion this results in type 2 diabetes." (PMID 35802167, 2022). "Overall, S. aromaticum has the potential to exert type 2 diabetes through phosphorylation pathways that modify insulin signaling, activation of receptor PPAR-γ ligand binding activity, and activation of AMPK and SIRT1 pathways." (PMID 36313111, 2022). "In the preclinical stage of type 2 diabetes, pancreatic beta‐cells augment insulin secretion to offset the defect of insulin action." (PMID 35913467, 2022).
type 2 diabetes (continued). "In humans, amino acid changes in KLF11 are associated with maturity onset diabetes of the young type VII, whereas complete inactivation of this pathway by the -331-insulin mutation causes neonatal diabetes mellitus." (PMID 35413089, 2022). "Of the 28 patients with type 2 diabetes, 11 (39.3%) were using a combination of insulin with metformin, empagliflozin, and/or glipizide." (PMID 36121652, 2022). "If GIPR agonism induced by tirzepatide treatment is responsible for enhanced ß-cell secretion, it is reasonable to assume a time-dependent process re-establishing GIP as an effective insulin secretagogue even in advanced type 2 diabetes." (PMID 36050763, 2022). "Our previous work on C. elegans ASNA-1 showed that ASNA-1 promotes insulin secretion and led later to the findings that insulin secretion is defective in ASNA1 knockdown mice leading to type 2 diabetes." (PMID 36480541, 2022). "We recruited hospitalized patients with type 2 diabetes who had stable glycemic control with insulin degludec (≤16 units/day) and taking a DPP-4 inhibitor." (PMID 35097130, 2022). "The strength of this review is that it is, to our knowledge, the only systematic review exclusively analyzing insulin subtypes and dosing strategies for insulin-treated type 2 diabetes during Ramadan." (PMID 35634376, 2022). "Some PTPs, such as PTPN1, PTPN2, PTPN9, PTPN11, PTPRS, and DUSP9, have been shown to attenuate insulin signaling and trigger type 2 diabetes, indicating that PTPs are promising drug targets for the treatment or prevention of type 2 diabetes." (PMID 35204821, 2022). "Many patients diagnosed initially with type 2 diabetes also require insulin injections in the long term." (PMID 35705561, 2022). "Type 2 diabetes (T2D) is a multifactorial, heritable syndrome characterized by dysregulated glucose homeostasis that results from impaired insulin secretion and insulin resistance." (PMID 35305202, 2022). "This genus was demonstrated to be positively correlated with insulin and elevated in type 2 diabetes patients." (PMID 35637874, 2022). "Insulin therapy for type 2 diabetes usually is necessary after a longer duration of the disease due to its inherent tendency to progress in terms of insulin secretion capacity getting lower over time." (PMID 35942330, 2022). "Evidence supports the significance of dietary patterns in the management of type 2 diabetes, as it influences a great number of cardiometabolic factors including glucose insulin homeostasis and blood pressure." (PMID 35071669, 2022). "Resistance to regeneration of insulin-producing pancreatic β cells is a fundamental challenge for type 1 and type 2 diabetes." (PMID 35700053, 2022). "Type 2 diabetes mellitus (T2DM) occurs when the blood glucose level rises excessively because the ineffective body use of insulin." (PMID 35268080, 2022). "Troglitazone as a type 2 diabetes oral medication, has the effect of improving the sensitivity of muscle and adipose tissue to insulin and inhibiting hepatic gluconeogenesis." (PMID 35749386, 2022). "Many genes were affected similarly by type 2 diabetes and obesity, although others (e.g. INS) were increased in obesity but reduced in type 2 diabetes." (PMID 35482056, 2022). "It seems apparent that insulin stimulation weakens signaling pathways in the lymphocytes of people with obesity or type 2 diabetes." (PMID 35711466, 2022). "In response to 8-week HIIT, insulin-stimulated GDR (mg/min/m2) increased by 42% in men with type 2 diabetes (p<0.001), 27% in obese men (p=0.001) and 29% in lean men (p<0.001)." (PMID 36387850, 2022). "The NAFLD liver fat score (NLFS) incorporates metabolic syndrome, type 2 diabetes status, fasting insulin level, and fasting aspartate aminotransferase/alanine aminotransferase ratio, and has an 86% sensitivity in detecting NAFLD." (PMID 36458039, 2022).
type 2 diabetes (continued). "To assess this, we compared the glycemic profile of patients with type 1 and insulin-treated type 2 diabetes using flash glucose monitoring (FGM), before and during lockdown including the holy month of Ramadan." (PMID 35433783, 2022). "The lipid droplets and fatty acids associated with liver steatosis in turn can affect many signaling pathways including insulin signaling to promote diabetes mellitus type II." (PMID 36187787, 2022). "Whereas, in type 2 diabetes, insulin secretion/sensitivity is impaired resulting in reduced production of insulin which invariably leads to decrease in hepatic glucose conversion to glycogen, cumulating in a high level of glucose in the blood." (PMID 35432973, 2022). "The combination of 2-O-M with insulin enhances the function of insulin-induced glucose-lowering effect through activation of insulin signaling pathway in both type 1 diabetes mice and type 2 diabetes mice models." (PMID 35502441, 2022). "Many subtypes within type 2 diabetes have been shown to be effectively treated with sulfonylureas and insulin in case reports." (PMID 36573710, 2022). "Improvement in glycaemic control is the key objective of type 2 diabetes management and can involve changes in insulin secretion, insulin sensitivity, or both." (PMID 35294578, 2022). "Type II diabetes mellitus (DMT2) is a debilitating disease characterized by high blood glucose levels secondary to either insufficient insulin secretion or a combined effect of insulin resistance and its inadequate production." (PMID 35530852, 2022). "In the 1990s, three drugs that improved insulin sensitivity (troglitazone, rosiglitazone, and pioglitazone) were approved for the treatment of type 2 diabetes." (PMID 35782864, 2022). "In the present study, the mean glucose level, prevalence of type 2 diabetes, and use of exogenous insulin treatment were higher in the high GV group than in the low GV group." (PMID 36575485, 2022). "Ultimately, everyone having diabetes type-I, and, importantly, having diabetes type-II, need insulin treatment." (PMID 35723344, 2022). "While these ages are representative of patients with type 2 diabetes receiving subcutaneous injections of insulin in Denmark, it is acknowledged that age alters skin microbiome, particularly with changes in diversity." (PMID 35460122, 2022). "For example, an industry-funded trial examining the insulin sensitizing drug Rosiglitazone in type 2 diabetics demonstrated a highly statistically significant primary surrogate outcome (fasting plasma glucose)." (PMID 35323717, 2022). "The use of the web-based GlucoonlineTM system for 6 months resulted in improved glucose control in patients with insulin-treated type 1 and type 2 diabetes, as compared to standard of care." (PMID 35476320, 2022). "Type 2 diabetes, on the other hand, occurs when the body is incapable of generating enough insulin, or when the insulin that is produced is ineffective." (PMID 35159679, 2022). "Knockdown of human or C. elegans ASNA1/ASNA-1 protein leads not only to cisplatin sensitivity phenotype but simultaneously results in decreased insulin secretion and type 2 diabetes in mice." (PMID 36480541, 2022). "Our western blotting results showed that STZ-treatment markedly downregulated SIRT4 expression, which was consistent with the results of previous studies in a mouse model of type-2 diabetes and insulin-resistant rats." (PMID 35956936, 2022). "In another study, scopoletin (1 mg/kg) reduced blood glucose, insulin, and lipid levels in high-fructose diet-induced type 2 diabetes, involving the activation of IRS1, PI3K, and Akt phosphorylation." (PMID 36330088, 2022). "The findings demonstrate that irrespective of the mode of training, exercise training is an important technique for enhancing certain insulin resistance-related adipocytokines in type 2 diabetes patients." (PMID 36404859, 2022).